INS (insulin)
Diseases named in the same sentence as INS in open-access papers (continued):
Sharing a sentence is not in itself a finding about the gene and the disease.
diabetes (continued). "The proband (F1957-II-1) has been treated with insulin (40 U/day) for 20 years since she was first diagnosed with diabetes at the age of 40." (PMID 31143779, 2019). "Diabetes (Type II) is a multifactorial disease characterized by dysfunction of insulin action (insulin resistance) and failure of insulin secretion by pancreatic β-cells." (PMID 30875980, 2019). "From restoring insulin function in diabetics to restoring locomotion in individuals affected by paralysis, each new discovery brings us closer to treating even the most intractable diseases so that individuals can live in health, unencumbered by sickness." (PMID 30521112, 2019). "Although synthetic oral hypoglycemic drugs alongside insulin are the main route for controlling diabetes, they fail to reverse the course of its complications completely and further worsen it by the fact that they also demonstrate prominent side effects." (PMID 31575072, 2019). "The classic counterregulatory effect of insulin exerted by GH justifies the high rates of glucose intolerance and diabetes mellitus found in patients with acromegaly, where excess GH induces insulin resistance." (PMID 31939483, 2019). "The collected serum from different groups of zebrafish (healthy group, diabetes group, insulin-treated group, and the group treated with the plant extract at doses of 1, 2, and 3 g/kg were analyzed using LC-MS to investigate their serum fingerprints." (PMID 30999617, 2019). "Studies using mesenchymal stromal cells (MSCs) as a source of insulin-secreting cells (IPCs) are a promising path in the pursuit for diabetes therapy." (PMID 31109026, 2019). "As a new anthropometric measure of lipid over accumulation, the accurate predictive value of lipid accumulation product index (LAP) in insulin sensitivity, diabetes and metabolic syndrome is also documented." (PMID 31297161, 2019). "The majority of participants in both groups had diabetes for five years or longer (81.6%), had been taking insulin for less than five years (77.2%), and used a reusable insulin pen (94.1%)." (PMID 31514391, 2019). "Hyperglycemia and resistance to the glucose-clearing effects of the hormone insulin are both pathological hallmarks of diabetes." (PMID 31156558, 2019). "A treatment with tauroursodeoxycholic acid, which is known to alleviate ER stress, significantly reduced the incidence of diabetes and raised insulin secretion." (PMID 31822470, 2019). "Of the total diabetes patients who were undergoing diabetes treatment, 90,182 (90.4%) were treated with oral agents and 7049 (7.1%) were treated with oral agents and insulin injection." (PMID 31726788, 2019). "In summary, this study represents the first of its kind from Taiwan to evaluate the real-world clinical benefits of switching Taiwanese diabetes patients from Gla-100 to Gla-300 insulin therapy in reducing nighttime glucose variability by means of CGM." (PMID 31346529, 2019). "The poorer glycaemic control with insulin treatment was possibly related to the disease progression and the fact that clinicians prescribe insulin to patients with most advanced diabetes." (PMID 31023374, 2019). "Serum ucOC and OC concentrations remained significant factors even after adjusting for gender, HbA1c, body weight-adjusted total daily dose of insulin and duration of diabetes (β = -0.260, P = 0.027; β = -0.254, P = 0.031, respectively)." (PMID 31050684, 2019). "Recent studies suggest that podocytes can be the direct target of circulating hormones, lipids, adipokines and insulin in diabetes." (PMID 31200589, 2019). "Diabetes in obese people occurs mostly due to insulin resistance and subsequent hyperinsulinemia through adipogenesis and the insulin signaling pathway." (PMID 30934943, 2019). "Many of these genes have previously known roles in regulating metabolic processes related to obesity, diabetes, and specific processes related to insulin secretion." (PMID 31300714, 2019).
diabetes (continued). "This study included 50 renal transplant patients and showed that a 3-month treatment of neutral protamine Hagedorn insulin decreased HbA1c and the occurrence of diabetes (73%) in the treated group." (PMID 31227028, 2019). "Being females, use of insulin, longer duration of diabetes, and presence of diabetes complications were significantly related to the average annual cost per patient." (PMID 31455307, 2019). "Diabetes mellitus (DM) is one of the devastating disease characterized either by absolute insulin deficiency due to the destruction of β cells (Type 1) or by relative insulin deficiency due to the reduced insulin sensitivity in peripheral cells (Type 2)." (PMID 31015367, 2019). "At present, the main treatments for diabetes include diet control, regular blood glucose testing, oral hypoglycemic chemotherapy and insulin supplementation." (PMID 32038250, 2019). "This is currently a hypothetical form of drug administration for EPO as it would require a programmable EPO pump similar to insulin pumps used to treat patients with diabetes mellitus." (PMID 31630225, 2019). "Intranasal delivery of insulin is an alternative approach to treat diabetes, as it enables higher patient compliance than conventional therapy with subcutaneously injected insulin." (PMID 31210056, 2019). "Previous studies suggest that the beneficial effects of structured exercise intervention programs on diabetes management are primarily realized through improved insulin sensitivity and blood glucose control." (PMID 30804739, 2019). "The objective of the present study was to determine the effectiveness of insulin analogs compared with human insulin in the treatment of pregnant women with diabetes through a systematic review with meta-analysis." (PMID 30786308, 2019). "Administering daily insulin injections at a fixed time and frequency can be difficult for people with diabetes owing to variations in daily routine." (PMID 30369394, 2019). "A Median regression analysis showed that female gender, use of insulin, longer duration of diabetes, and presence of complications are the factors related to a higher annual average cost per person." (PMID 31455307, 2019). "Fasting insulin was measured by the electrochemiluminescence method and classified according to the Guidelines of the Brazilian Diabetes Society, which considers high fasting plasma insulin higher than 15 μU/mL." (PMID 31933541, 2019). "The advantage of a disease-specific tool is to provide a more detailed assessment of specific diabetes management skills including carbohydrate counting, insulin injections, insulin pump management, interfacing with insurance providers, and sick day rules." (PMID 30891310, 2019). "As insulin signaling is an ageing factor, our results help to connect several important phenotypes, namely ageing, AD and diabetes, through insulin signaling." (PMID 30652125, 2019). "Using the old and new definitions of diabetes mean fasting glucose was 125.1 mg/dL vs. 117.4 mg/dL, mean fasting insulin was 20.9 mIU/Lvs." (PMID 31513598, 2019). "Type 2 diabetes mellitus (T2DM) is characterized by persistent hyperglycemia and is primarily caused by pancreatic β-cell dysfunction and insulin resistance in target organs." (PMID 31417608, 2019). "A standard drug prescribed to patients is metformin, which can re-sensitize insulin signaling in diabetes." (PMID 31068799, 2019). "This can be attributed to insulin resistance promoting both hypertension and diabetes (Sowers) or a myriad of genetic and environmental factors contributing to the development of both diabetes and hypertension." (PMID 31883041, 2019). "Several studies have examined the effects of ACVR2B/Fc treatment on insulin signaling in obesity and diabetes, but this is the first report demonstrating the effects on cachexia." (PMID 31438622, 2019). "For the management of diabetes, this complex micelle was shown to useful for self-regulated insulin delivery." (PMID 31756981, 2019).
diabetes (continued). "Weight gain during insulin therapy can be a challenging problem in already overweight patients with type 2 diabetes mellitus affecting treatment compliance and long-term prognosis." (PMID 31576267, 2019). "While this model is simple and cannot be solved analytically, its ability to return estimates for glucose effectiveness and insulin sensitivity, which are key parameters for diabetes diagnosis, is advantageous." (PMID 31829209, 2019). "Hypoglycaemia (low plasma glucose) is a serious and potentially fatal complication of insulin-treated diabetes." (PMID 30635569, 2019). "Recent studies have shown that IT can regulate the expression of insulin in vivo, stabilize blood glucose regulation, delay progression of clinical symptoms of diabetes, and even reverse related renal and myocardial damage." (PMID 31583254, 2019). "The drug treatments for diabetes currently include insulin, insulin secretagogues, promotion of peripheral tissue glucose use, inhibition of intestinal glucose absorption, and insulin sensitizers." (PMID 31511772, 2019). "The use of medication to better control diabetes was reported by only one included study with the group who used insulin presenting a higher prevalence of chronic conditions, including low back pain." (PMID 30789940, 2019). "For example, we identified 38,045 participants who had refilled at least two prescriptions for a given non-insulin diabetes medication class." (PMID 30759121, 2019). "Optimal type 1 diabetes mellitus (T1D) care requires lifelong appropriate insulin treatment, which can be provided either by multiple daily injections (MDI) of insulin or by continuous subcutaneous insulin infusion (CSII)." (PMID 31685014, 2019). "Insulin is the universal treatment for diabetes since the 20th century, since it is a physiological glucose-lowering agent." (PMID 31652990, 2019). "For example, impact indicators on diabetes link to preceding diabetes-related performance indicators e.g. hospitalizations, managed insulin-levels, and capacity indicators e.g. prevention services for diabetes, existence of patient registries." (PMID 31881884, 2019). "Diabetes refers to a group of lifelong metabolic diseases characterized by chronic hyperglycemia due to insufficient insulin secretion and/or biological dysfunction." (PMID 31217790, 2019). "During follow-up, additionally one patient was diagnosed with diabetes and treated with insulin, and 18 with diabetes which was treated with oral medication." (PMID 30783963, 2019). "In another study, it was demonstrated that a diabetes application was likely to give a recommendation for an inappropriate insulin dosage to its user." (PMID 30488379, 2019). "Among CKD participants with diabetes, factors associated with a CVE were RRT (HR 3.58, 95% CI [2.16;5.93]) and insulin treatment (HR 1.87, 95% CI [1.06;3.30])." (PMID 31324183, 2019). "As such, elevated blood glucose levels observed in diabetes patients are treated with exogenous insulin." (PMID 31244777, 2019). "Intensive control of blood glucose levels through the use of oral hypoglycaemic agents and insulin have been used to treat diabetes but they have proven to be ineffective in the prevention of the vascular complications of diabetes." (PMID 30886586, 2019). "The influence of insulin treatment on the development of diabetes-related microvascular complications has been sparsely investigated." (PMID 31890395, 2019). "Just over a third of patients (38%) were prescribed two non-insulin glucose-lowering diabetes medications and 16% were prescribed three." (PMID 30777033, 2019). "We do recommend for this to be followed-up in future studies specifically for patients with diabetes who are on insulin or on sulfonylureas." (PMID 30976298, 2019). "In type 2 diabetes, insulin secretion is reduced and abnormalities in β cell function are a major determinant of the rate of diabetes progression." (PMID 31478094, 2019).
diabetes (continued). "Those MSNs based systems have the potential to be developed as convenient and safe insulin delivery carriers for diabetes management." (PMID 31119124, 2019). "More than four out of five patients (N = 65,902, 84.7%) refilled prescriptions for any non-insulin diabetes medications within 90 days after insulin initiation." (PMID 30759121, 2019). "Almost all pregnancies among women with pre-existing diabetes continue treatment during the pregnancy, with 75% being treated with insulin." (PMID 31775682, 2019). "Insulin therapy is pivotal in the management of diabetes, with diabetic individuals taking multiple daily insulin injections." (PMID 31443473, 2019). "Insulin and multiple oral hypoglycemic agents, such as metformin, α-glucosidase inhibitors, sulfonylureas, and glibenclamide, are first-line anti-diabetes agents currently in use." (PMID 31443712, 2019). "Males had a high diabetes incidence that was increased by early overnutrition, characterized by a progressive increase in insulin secretion as well as β cell death, indicated by histological analysis and increased circulating miR-375 levels." (PMID 30842440, 2019). "Diabetes mellitus (DM) is one of the most common metabolic diseases in the world that results from defects in endogenous insulin secretion/action and thereby contributes to the impairment of glucose disposal (hyperglycemia)." (PMID 31089370, 2019). "We find that AAV2/8-insulin gene therapy can indeed correct hyperglycaemia in both of these models of diabetes, but that the dose requirements for success in autoimmune, spontaneously diabetic NOD mice is 7–10-fold higher than in non-autoimmune C57BL/6 mice." (PMID 30514969, 2019). "End‐of‐life diabetes care requires a holistic approach; blood glucose monitoring should be minimized and complex insulin regimens avoided." (PMID 31002426, 2019). "Key metabolic abnormalities in type 2 diabetes mellitus are hyperglycemia, hyperinsulinemia, systemic insulin resistance, and impaired cardiac insulin metabolic signalling." (PMID 30871282, 2019). "Given the importance of diabetes and its treatment, in the current study, a plasmid construct for expressing the human insulin gene has been successfully designed and cloned." (PMID 32184874, 2019). "Individuals with higher SES inject insulin more frequently on a daily basis, are better informed about diabetes management and more of them attend structured education." (PMID 31604437, 2019). "IN glucagon appears to represent a major breakthrough in the treatment of severe hypoglycemia in insulin-treated patients with diabetes, both children and adults." (PMID 31349701, 2019). "In order to initiate insulin therapy earlier in disease process and to avoid serious complications resulting from poor glycemic control of diabetes, health education of both patients and primary healthcare physicians is warranted." (PMID 30881393, 2019). "Of note, the types of insulin regimens can also affect the occurrence of adverse events in patients with type 1 diabetes mellitus." (PMID 30938074, 2019). "Prevalent diabetes was defined as a fasting plasma glucose level ≥126 mg/dL, self-reported use of anti-diabetic treatment (insulin or oral anti-diabetic drugs), or diabetes diagnosis by a physician." (PMID 31319658, 2019). "Further studies including beta receptors’ communication in the treatment of diabetes mellitus as well as animal experiments involving the insulin secretion effect of their ligands are required." (PMID 30761839, 2019). "Previous studies showed that treatment with insulin injection affects depressive symptoms in diabetes patients." (PMID 31726788, 2019). "Specifically, the patient’s mother was on insulin therapy for diabetes mellitus which had been diagnosed during the first trimester of pregnancy, when she was 24 years of age." (PMID 29739729, 2019).
diabetes (continued). "New technologies such as continuous insulin pumps for type 1 diabetes and telemedicine-guided management of diabetes are significantly appreciated by patients and represent promising clinical tools." (PMID 31119029, 2019). "Diabetes is a group of metabolic diseases that can be diagnosed by Hyperglycemia and is due to impaired insulin secretion, insulin performance, or both." (PMID 31200678, 2019). "Hand hygiene practices were significantly lower in people with diabetes treated with insulin compared to untreated people and those treated with an oral hypoglycemic agent." (PMID 30974788, 2019). "This highlights the prudence of further study into the antidiabetic properties of M. charantia, and the role of p-insulin as a potential insulin replacement in patients with diabetes." (PMID 31516543, 2019). "Development of diabetes was assessed by measuring fasting levels of glucose, insulin and HbA1c and by calculating HOMA indices." (PMID 30998801, 2019). "Considering obesity is a cause of the vast majority of T2DM diabetes, one underlying pathogenic mechanism could involve inflammation within adipose tissue with production of cytokines that interfere with insulin signaling, leading to resistance to insulin and decreased glucose clearing." (PMID 31847392, 2019). "Blood levels of the BCAAs are typically elevated in Ob, insulin-resistant humans, and models of diet-induced diabetes." (PMID 30651891, 2019). "The current approaches for the treatment of diabetes mostly depend on insulin injection and oral antidiabetic agents." (PMID 31583253, 2019). "This indicated that the anti-hyperglycemic effect of sitagliptin, in the current rat model of HFD/STZ-induced diabetes, was mostly afforded through an insulin secretagogue effect and increasing peripheral glucose utilization." (PMID 31881657, 2019). "Glucagon-like peptide 1 (GLP-1) stimulates insulin secretion and reduces blood glucose in type 2 diabetes mellitus (T2DM)." (PMID 30700996, 2019). "Npy was increased by more than 1.5-fold in the midbrain (the hypothalamus was included in this region in this study) of transgenic mice in the PM during diabetes despite high levels of insulin." (PMID 31601900, 2019). "We denote the four major factors related to the development of type 2 diabetes (T2D) as “diabetes factor” (DF); increased insulin resistance (IR); decreased glucose effectiveness (GE); and the first-and-second-phase of insulin secretion (FPIS, SPIS)." (PMID 31482956, 2019). "Currently, management of diabetes mainly focuses on insulin or its peptide derivatives, anti-diabetic oral drugs, and diet control." (PMID 31835292, 2019). "FLI includes body mass index (BMI), waist circumference, gamma-glutamyl transferase, and triglyceride; NAFLD includes diabetes, fasting insulin level, fasting aspartate-aminotransferase (AST), and AST/alanine transaminase ratio." (PMID 30674308, 2019). "It has been argued that the dysregulation in PI3K/AKT pathway operates between two extremes states leading to either diabetes or cancer, wherein the insulin activity is either reduced or increased, respectively." (PMID 31653897, 2019). "One of the aims of cell-based therapy in diabetes is to generate new islet-like structures morphologically and functionally similar to human pancreatic islets and that can sense glucose and secrete insulin in response." (PMID 30191384, 2019). "Intraperitoneal (IP) insulin administration is a last‐resort treatment option for selected patients with type 1 diabetes mellitus (T1DM)." (PMID 31592137, 2019). "Insulin resistance, a pathological condition characterized by defects in insulin action leads to the development of Type 2 diabetes mellitus (T2DM), a disease which is currently on the rise that pose an enormous economic burden to healthcare systems worldwide." (PMID 31234300, 2019).